AHR (aryl hydrocarbon receptor)
Diseases named in the same sentence as AHR in open-access papers (continued):
Sharing a sentence is not in itself a finding about the gene and the disease.
Chronic colitis (7 papers, 2016 to 2025). A chronic inflammatory disease of the large intestine (colon, cecum and rectum). "Gut: depletion of dietary IC is fatal in AhR IEC-deficient mice and worsens chronic colitis in C57BL/6 mice; in contrast, its administration reduces the Th17/Treg ratio in the same model." (PMID 38675450, 2024). "Together, these data indicate that activation of AhR through dietary I3C is able to restore tight junction expression in chronic colitis." (PMID 38068838, 2023). "Collectively, these data indicate that the removal of AhR from IECs exacerbates DSS-induced chronic colitis." (PMID 38068838, 2023). "Indole-3-carbinol (I3C), a ligand of AhR derived from plants, exhibits promising therapeutic potential in the context of DSS-induced chronic colitis." (PMID 41019044, 2025). "In summary, our data demonstrated that L-fucose played a therapeutic role in ameliorating DSS-induced chronic colitis in mice by accelerating ISC proliferation, and it works through the AHR/IL-22 pathway of LPMCs." (PMID 36432480, 2022). "Similar to constitutively deleted IEC AhR in acute inflammation, our current studies utilizing mice with inducible deletion of IEC AhR induced with chronic colitis showed increased severity of inflammation while providing novel insights into the underlying mechanism." (PMID 38068838, 2023).
eczema (7 papers, 2014 to 2024). "In mice, in utero exposure to TCDD increased epidermal barrier formation via activation of the AhR and increased expression of the filaggrin gene; a deficiency and mutation in filaggrin has been associated with eczema." (PMID 29482571, 2018). "More likely, increased PM2.5 exposure would influence the risk of eczema, potentially through modulation of the aryl hydrocarbon receptor (AhR) pathway and generation of oxidative stress, leading to impairment in the epidermal barrier and associated inflammation." (PMID 39536018, 2024). "It has also been suggested that AhR expression levels in peripheral blood mononuclear cells are higher than in AD patients and may be associated with eczema area and severity index scores." (PMID 37623895, 2023). "Another AhR-mediated mechanism by which TCDD may impact eczema risk is by affecting the skin barrier." (PMID 29482571, 2018). "Therefore, there may be an interplay of dermatological and immunomodulatory responses from TCDD’s interaction with AhR, resulting in lower risk of eczema." (PMID 29482571, 2018). "Activation of AhR in keratinocytes has been shown in mice to induce an eczema phenotype with severe, pruritic skin lesions as well as a T helper 2 (Th2)-mediated immune response." (PMID 39536018, 2024). "Individuals with eczema may be at increased risk for transcutaneous PM2.5 absorption and subsequent activation of the AhR pathway given that penetration of PM2.5 into skin tissue is enhanced by disruption of the skin barrier." (PMID 39536018, 2024). "PM2.5 as a whole may contribute to the development or exacerbation of eczema by inducing skin barrier dysfunction, oxidative damage, and inflammatory dysfunction via modulation of the aryl hydrocarbon receptor (AhR) pathway." (PMID 39536018, 2024). "This conclusion is consistent with epidemiologic data showing that environmental pollution with specific AhR activators (polycyclic aromatic hydrocarbons, PAHS) is related to higher numbers of eczema appearance in patients." (PMID 35458697, 2022).
HIV-1 infection (7 papers, 2018 to 2024). The type species of lentivirus and the etiologic agent of acquired immunodeficiency syndrome (AIDS). "The finding that AHR is playing a role in the modulation of HIV-1 infection can explain the correlation between cellular Trp metabolism and HIV pathogenesis, and it also provides new host targets for the treatment of HIV-1 infection." (PMID 31848275, 2019). "Having demonstrated a role of AHR ligands in reactivating HIV-1, we went on to investigate mechanistically how AHR modulates HIV-1 infection." (PMID 31848275, 2019). "Next, we used quantitative PCR assays to monitor HIV-1 DNA synthesis during HIV-1 infection of macrophages, and found that viral DNA synthesis was profoundly inhibited by AhR activation." (PMID 30132758, 2018). "Conversely, AhR can also serve as a hindrance to HIV-1 infection by means of CD4+ T cells." (PMID 38680494, 2024). "It is postulated that targeting the downstream effects of AhR may be pivotal in controlling HIV-1 infection." (PMID 38680494, 2024). "However, it was recently reported that AHR is activated by Trp metabolites to favor HIV-1 infection and reactivation, suggesting a novel role for AHR in AIDS." (PMID 33746961, 2021). "Similarly, tryptophan metabolism promotes HIV-1 infection and transcription by the activation of a ligand-activated transcription factor aryl hydrocarbon receptor (AHR) in CD4+ T cells." (PMID 34616406, 2021). "Taken together, these data demonstrate that AHR is a positive regulator of HIV-1 infection." (PMID 31848275, 2019). "AhR activation can have a variety of effects on cells that could plausibly lead to inhibition of HIV-1 infection, including STAT1 activation (that might active expression of antiviral genes) or inhibition of cell cycle progression." (PMID 30132758, 2018). "If the block in HIV-1 infection induced by AhR activation in macrophages was primarily caused by SAMHD1 dephosphorylation and consequent dNTP depletion, we reasoned that infection in the presence of Vpx should reduce or abolish the inhibitory effect of AhR activation." (PMID 30132758, 2018). "This study demonstrates that Trp metabolites augment the activation of aryl hydrocarbon receptor (AHR), a ligand-activated transcription factor, to promote HIV-1 infection and transcription." (PMID 31848275, 2019). "In this study, we demonstrated that the aryl hydrocarbon receptor (AHR), a ligand-activated transcription factor, is activated by Trp metabolites to promote HIV-1 infection and reactivation." (PMID 31848275, 2019).
hydronephrosis (7 papers, 2009 to 2026). Collection of urine in the renal pelvis that results in dilatation of the renal pelvis and calyces. "Mouse models of hydronephrosis, in which hydronephrosis is induced chemically, e.g., by administering 2,3,7,8-tetrachlorodibenzo-p-dioxin, which activates aryl hydrocarbon receptor signaling, or physically, e.g., by ureteral ligation, have been created." (PMID 39000307, 2024). "However, in AHR-KO rats, hydronephrosis and hydroureter were observed and AHR was found to play significantly different roles in tissue development and virulence in rodent species." (PMID 36668758, 2022). "Human AHR can be expressed in mice to mediate the development of TCDD-induced hydronephrosis." (PMID 36668758, 2022). "It should be noted that AhR is required for the urinary tract development in a species-specific manner because the absence of AhR in rats causes hydroureter and hydronephrosis even in the absence of an exogenous ligand." (PMID 30708991, 2019). "Based on the significant role of AhR in determining susceptibility to TCDD toxicities, activation of AhR in the outer zone of medulla may be responsible for the onset of hydronephrosis." (PMID 30708991, 2019). "In this regard, cleft palate and hydronephrosis, two of the teratogenic end points of dioxin exposure during mouse embryonic development, might be the result of the derailment of endogenous AHR morphogenetic functions." (PMID 19654925, 2009). "In contrast to rats, mice lacking AHR did not develop hydronephrosis or hydronephrosis in the absence of TCDD." (PMID 36668758, 2022). "In contrast to rats, mice lacking AhR do not develop hydroureter or hydronephrosis in the absence of TCDD, suggesting that AhR has diverse roles in tissue development across species." (PMID 30708991, 2019).
lipid metabolism disorders (7 papers, 2021 to 2025). "This review summarizes the relationship between AhR and lipid metabolism disorders, as well as the interaction between gut microbiota and AhR, exploring how this interaction modulates host lipid metabolism." (PMID 39944639, 2025). "Fourth, AhR-induced oxidative stress and inflammatory responses form a vicious cycle with lipid metabolism disorders, collectively driving disease progression." (PMID 41585883, 2025). "Lactobacillus supplementation can efficiently activate AhR, subsequently reducing hepatic lipid accumulation and serum triglyceride levels, thereby improving lipid metabolism disorders." (PMID 37894615, 2023). "In summary, MFE effectively attenuated inflammation and lipid metabolism disorders in mice with NAFLD through the NF-κB and AhR–FAS pathways." (PMID 35565666, 2022).
Nystagmus (7 papers, 2013 to 2025). Rhythmic, involuntary oscillations of one or both eyes related to abnormality in fixation, conjugate gaze, or vestibular mechanisms. "Equally, loci associated with foveal hypoplasia, nystagmus and hypopigmentation (AHR, FRMD7, GPR143, and SLC38A8) were assessed for SNV or SV segregating with disease." (PMID 38383453, 2024). "AHR deficient mice present nystagmus (rapid involuntary eye movements) and show increased RPE autofluorescence, sub-RPE deposits, and RPE degeneration in older mice." (PMID 35295218, 2022). "Further study of these AHR knockout mice revealed that the mice with nystagmus also have deficiencies in the optic nerve myelin sheath." (PMID 35295218, 2022). "The goal of our work is to investigate the biochemical consequences of the nystagmus-linked p.Q621∗ AHR mutation." (PMID 33193710, 2020). "It should be noted that for the AhR−/−, the nystagmus frequency is in range or close to the range of the table frequencies tested, which makes it impossible to discriminate if the eye movement is caused by the nystagmus or in response to the head movement." (PMID 23301081, 2013). "It was recently published that AHR-KO are afflicted by a nystagmus and found to have an impaired optic nerve myelin sheath along with modifications in lipid composition and in the expression of MAG." (PMID 33193710, 2020). "We previously demonstrated that AhR is expressed during development of the central nervous system(CNS) and that its deletion leads to the occurrence of a congenital nystagmus." (PMID 28851966, 2017). "The developmental expression of the AhR in the sensory cells responsible for the OKR would be compatible with the presence of a congenital nystagmus of visual origin." (PMID 23301081, 2013). "In contrast, the pattern recorded in the AhR−/− mice is perturbed by the presence of the spontaneous nystagmus superimposed to the optokinetic response." (PMID 23301081, 2013). "Overall, the presence of a spontaneous nystagmus in mice of different ages and gender, demonstrates that the AhR−/− mice consistently suffer from impairment in gaze control." (PMID 23301081, 2013). "First, AhR KO mice display as early as on P26 a nystagmus that rapidly aggravates with age." (PMID 28851966, 2017). "In contrast, in AhR−/− mice, the spontaneous nystagmus overlaps with the former described pattern." (PMID 23301081, 2013). "However, decrease in optokinetic reflex, influence of light on the nystagmus, developmental expression of AhR in the retina and the observed disorganization of retinal cell layers all suggest that the nystagmus is likely of visual or visuo-motor origin." (PMID 23301081, 2013). "Interestingly, the AhR-knockout (AhR-KO) adult mice display a spontaneous horizontal nystagmus." (PMID 30097849, 2019). "In order to identify the signaling pathways involved in all observed phenomenon at the functional, cellular and molecular levels (nystagmus, demyelination, MAG expression), we investigated the transcriptomes of the AhR-KO and WT optic nerves." (PMID 28851966, 2017). "Together with the influence of light on the nystagmus and with the decrease in the OKR efficiency, these results point toward a role of the AhR in the development of the visuo-motor system." (PMID 23301081, 2013). "Our interpretation is that despite the obvious impairment in gaze stabilization caused by the nystagmus, the 3 neurons-arc which constitutes the basic circuitry underlying the vestibulo-ocular reflex is functional and probably not directly affected by the AhR defect." (PMID 23301081, 2013). "At P26, the nystagmus was present in all AhR-KO mice, while it was never observed in WT-control mice." (PMID 28851966, 2017). "We have previously shown that the origin of the nystagmus was not vestibular neither cerebellar, while the AhR was expressed in the eye during mice development." (PMID 28851966, 2017).
Nystagmus (continued). "The presence of a congenital nystagmus in the AhR−/− mice and the deficit in the OKR reflex suggest that the AhR might play a developmental function in the visuo-motor system." (PMID 23301081, 2013). "Together with the absence of obvious deficits in postural control (data not shown), these results suggest that the nystagmus of AhR−/− mice is unlikely to be of purely vestibular origin." (PMID 23301081, 2013). "The fact that CYP1A1 and TiPARP genes are not induced upon BA-activation of AHR in the heterozygotes, who do not exhibit the nystagmus phenotype, might suggest that their gene products are not involved in the ocular pathology observed in the homozygous patients." (PMID 33193710, 2020). "After 5 weeks of treatment, we did not observe any abnormal eyes movements, i.e no nystagmus was present, suggesting that in adult mice TCDD does not alter the putative physiological functions of the AhR related to the regulation of the gaze stabilizing homeostasis." (PMID 23301081, 2013).
autoimmune hepatitis (6 papers, 2021 to 2025). Hepatitis caused by autoantibodies. "In support of this notion, AHR dysfunction has been recently linked to autoimmune hepatitis." (PMID 34075438, 2021). "High expression of AHRR (AHR repressor) and HIF-1α inhibits AHR signaling in Th17 cells and regulatory T cells (Tregs) in autoimmune hepatitis (AIH)." (PMID 37692495, 2024). "In the current study, we used TCDD, a high affinity AhR ligand to study the impact of AhR activation in the murine model of autoimmune hepatitis (AIH)." (PMID 35720411, 2022). "In a murine model of autoimmune hepatitis, hepatic IDO1 activation accelerates the Kyn pathway, which via AhR signaling attenuates Th17 differentiation, expands Tregs, and suppresses Akt phosphorylation, ultimately ameliorating liver injury." (PMID 40963608, 2025). "Additionally, a previous study also suggests that binding of AhR with Erα exhibits higher affinity compared to ARNT, and alterations of AhR signaling significantly influence the functions of Tregs in autoimmune hepatitis." (PMID 36601108, 2022).
autoimmune uveitis (6 papers, 2018 to 2025). An autoimmune form of uveitis (disease). "In the first study, AhR knockout (AhR−/−) mice demonstrated increased apoptosis in the context of experimental autoimmune uveitis (EAU), as evidenced by TUNEL staining, which indicated a higher number of apoptotic cells compared to wild-type mice." (PMID 39791758, 2025). "In an autoimmune uveitis murine model, AhR was shown to regulate immune responses through STAT/NF-κB signaling and the subsequent production of pro-inflammatory cytokines, including TNF-α, IL-6, and IL-1β." (PMID 41300485, 2025). "In the ocular compartment, AhR knockout triggers apoptosis and inflammation in experimental autoimmune uveitis." (PMID 33143743, 2020). "This study shows that AhR, a ligand-activated nuclear receptor, has a profound effect on the development of autoimmune uveitis in mice." (PMID 30090104, 2018). "AhR agonists also reversed pro-inflammatory gene expression in experimental autoimmune uveitis." (PMID 33143743, 2020).
chronic lymphocytic leukemia (6 papers, 2020 to 2025). "For example, IL4I1-generated Trp metabolites activate AHR and suppress adaptive immunity, correlating with poorer survival in glioblastoma patients and accelerated chronic lymphocytic leukemia (CLL) progression in mice." (PMID 41155173, 2025). "Here, we investigated the functional role of the IDO1/Kyn/AHR axis in chronic lymphocytic leukemia (CLL)." (PMID 35371054, 2022). "IL4I1 can activate aryl hydrocarbon receptor (AHR) and promote progression of cancer by enhancing chronic lymphocytic leukemia progression." (PMID 35778697, 2022). "In this study, we addressed the potential role of AHR and HIF-1α in chronic lymphocytic leukemia (CLL) development in vivo." (PMID 34572746, 2021).
chronic myeloid leukemia (6 papers, 2016 to 2024). "Conversely, diminished AhR signaling in acute and chronic myeloid leukemia (AML/CML) has been shown to drive leukemic stem cell maintenance and disease progression." (PMID 37958428, 2023). "It was noted that the expression of the AhR protein is substantially dependent on the silencing and overexpression of Dvl in chronic myelogenous leukemia cell lines." (PMID 37232717, 2023). "We investigated the possible role of aryl hydrocarbon receptor (AhR) in this capability of urolithin A. We analyzed the ability of PBMCs preincubated with urolithin A, AhR agonist or antagonist to kill K562 (human chronic myelogenous leukemia) target cells." (PMID 39850551, 2024).
colon adenocarcinoma (6 papers, 2014 to 2023). "An early study discovered the link between AhR and colon neoplasia when they characterised the association of AhR with the human colon adenocarcinoma cell line LS180." (PMID 32456012, 2020). "Further correlation between AhR and tumor mutational burden (TMB) and microsatellite instability (MSI) has been reported in both colon adenocarcinoma and thymoma, and a correlation between AhR and MSI in colon and rectum adenocarcinomas has been reported." (PMID 37241719, 2023). "Importantly, the elevated AhR protein levels were also found in isolated EpCAM+ tumor epithelial cells, which were prepared from a subset of patient samples diagnosed as colon adenocarcinomas, as well as from the corresponding adjacent normal tissue collected during operations." (PMID 36077780, 2022).
cutaneous squamous cell carcinoma (6 papers, 2018 to 2024). "AhR was identified as a new risk factor for cutaneous squamous cell carcinoma (SCC) in a genome-wide association study." (PMID 35458697, 2022). "Aryl hydrocarbon receptor (AhR) provides a deeper insight into the pathogenesis of cutaneous squamous cell carcinoma (cSCC)." (PMID 33178182, 2020). "In fact, AHR−/− mice developed 50% less UVB-induced cutaneous squamous cell carcinomas in a chronic photocarcinogenesis study than their AHR+/+ littermates." (PMID 30013037, 2018). "Immunohistochemical analysis was used to detect the expression of AHR, CYP1A1, EGFR, and Ki-67 in 10 actinic keratosis (AK) cases, 10 Bowen disease (BD) cases, 20 cutaneous squamous cell carcinoma (cSCC) cases and 20 normal skin samples." (PMID 30144817, 2018).